EIF4A3 (eukaryotic translation initiation factor 4A3)
Diseases named in the same sentence as EIF4A3 in open-access papers (continued):
Sharing a sentence is not in itself a finding about the gene and the disease.
cancer (continued). "Further studies are needed to develop more effective EIF4A3 inhibitors and apply them to treatment of cancers and other PTC-related diseases." (PMID 34458150, 2021). "Nevertheless, much remains to be clarified about EIF4A3 function in light of the complexity of gene expression regulation as well as the onset and progression of cancer." (PMID 34458150, 2021). "In various types of cancers, numerous studies have now documented a link between EIF4A3, SMC3, ESPL1, CDC25B, CCNA2, or AURKA and their response to therapy." (PMID 32454908, 2020). "Further analysis suggested that WIPI3 and eukaryotic translation initiation factor 4A3 (EIF4A3) coordinately regulated the cancer cell cycle by spliceosome as a result of the strong positive correlation between them." (PMID 32973867, 2020). "Several studies have reported on the role of EIF4A3 in cancer." (PMID 40092703, 2025). "circHIPK3 contains multiple sites for the same RBPs (e.g., DDX54, EIF4A3, FMR1, IGF2BP1, IGF2BP2, LIN28B and MOV10), many of which are involved in chemoresistance and organelle-like structures, such as Cajal body and P-body which are associated with cancer." (PMID 40061896, 2025). "Furthermore, to evaluate how cancer-associated variants affect protein–protein or protein–mRNA networks, we systematically analyzed the mutations in core NMD components (eRF1, EIF4A3, and SMG1)." (PMID 41189592, 2025). "Studies have shown that EIF4A3‐IGF2BP2 is an important pathway in prostate cancer, suggesting that the EIF4A3‐circDHTKD1‐IGF2BP2‐PFKL axis may have a potential function in other cancers, which warrants further investigation." (PMID 39022816, 2024). "EIF4A3, as an RNA helicase, plays an important role in transcription and post transcriptional regulation, and the interaction between EIF4A3 and RNA in cancer has been widely studied." (PMID 39868374, 2024). "Therefore, a systematic pan-cancer analysis of EIF4A3 is urgently needed to determine its potential as a biomarker for cancer screening, prognosis prediction, and therapy design." (PMID 37777564, 2023). "Furthermore, as a novel m6A suppressor, EIF4A3 was found to be correlated with numerous RNA modification genes in multiple cancer types." (PMID 37777564, 2023). "Our results suggest that EIF4A3 is highly expressed in most cancer types, including BLCA." (PMID 37180585, 2023). "Conversely, EIF4A3 expression is lower in 5 cancers, such as KIPAN, KIRC, THCA, PCPG and KICH." (PMID 37777564, 2023). "Few studies have determined the direct effect of EIF4A3 on cancer development." (PMID 37180585, 2023). "Additionally, we verified the expression of EIF4A3 in different cancers using TIMER 2.0 database, which is based on TCGA database." (PMID 37777564, 2023). "Furthermore, we performed a pan-cancer analysis to unveil the role of EIF4A3 in determining and influencing diverse cell fates in human pan-cancer progression." (PMID 37777564, 2023). "Similarly, a significant increase in EIF4A3 mRNA expression was found in cancer tissues compared with paracancerous tissues in the BLCA tissue samples (p < 0.01)." (PMID 37180585, 2023). "Moreover, eIF4A3 has been associated with RNA stress granule formation and maintenance, indicating another possible mechanistic link between the EJC and cancer." (PMID 36142288, 2022). "Recent studies have shown that EIF4A3 is significantly upregulated in several malignant tumors." (PMID 34458150, 2021). "Our data suggested that eIF4A3 might become an interesting target to regulate viral oncoprotein levels in HPV16-infected cancer cells." (PMID 33760064, 2021). "Some studies reported that eIF4A3 bound to lncRNAs and was involved in the development of cancer." (PMID 33924522, 2021). "The frequent observation that eiF4a3 is elevated in cancer indicates it may serve as an oncogene when over-expressed, but it is unknown which of the protein’s functions, such as participating in RNA metabolism or translational regulation of selenoproteins might contribute to malignancy." (PMID 41563517, 2026).
cancer (continued). "In WT systems, cancer-associated mutations (P114L, R116K, R166H, G309A, and R316W) that influence protein–mRNA interaction showed a stable RMSF, specifically in the closed conformation of yeast eIF4A (structurally similar to human eIF4A3) upon binding ATP and mRNA." (PMID 41189592, 2025). "Moreover, it could be proposed that targeting EIF4A3 within the NMD machinery could offer novel therapeutic avenues in cancers that can induce defective RNAs." (PMID 41189592, 2025). "This analysis is necessary to determine whether EIF4A3 can serve as a reliable biomarker for cancer screening, prognosis prediction, and to aid in the development of precise therapies for different types of cancer." (PMID 38827026, 2024). "In addition to its oncogenic function in cancer, EIF4A3 also impacts the immune microenvironment." (PMID 37777564, 2023). "We were thus prompted to consider that EIF4A3 might function as an oncogene in human cancer." (PMID 37777564, 2023). "Therefore we compared the EIF4A3 expression between cancer and adjacent tissues in TCGA (The Cancer Genome Atlas) dataset and explored its prognostic value and further validated it in the external GEO (Gene Expression Omnibus) (GSE32894, GSE32548, GSE31684, and GSE13507) datasets." (PMID 37180585, 2023). "Thus, EIF4A3 has potential value in clinical applications as a prognostic marker or therapeutic target, which may provide a new direction in cancer research and treatment." (PMID 34458150, 2021). "Therefore, some eIF4A3 inhibitors were developed as anti-cancer agents." (PMID 31379779, 2019). "Consistently, the mRNA and protein expressions of OTUB2, EIF4A3, and TPI1 were increased in TNBC tissues and cell lines, as compared to para-carcinoma tissues and MCF10A cells." (PMID 41857621, 2026). "Therefore, instead of measuring how EIF4A3 affects the global m6A modification level, characterizing the m6A modification status of genes with functional relevance may better reflect its role in cancers." (PMID 39550559, 2024). "We explored EIF4A3 expression and its prognostic value in BLCA in public datasets, including the TCGA (The Cancer Genome Atlas) and GEO (Gene Expression Omnibus)." (PMID 37180585, 2023). "The RNA-binding protein EIF4A3 was found to stabilize TCAM1P expression, highlighting the intricate regulatory network involving pseudogenes in cancer." (PMID 37627052, 2023). "Therefore, EIF4A3 may mainly act as a cancer-promoting gene in different cancer types." (PMID 37777564, 2023). "Eukaryotic translation initiation factor 4A3 (EIF4A3), assigned to the DEAD box protein family, has been reported to function as an RNA-binding protein (RBP) to play key roles in cancer progression via affecting mRNA stabilization." (PMID 37179359, 2023). "In this study, we firstly proposed that TCAM1P is cancer/testis pseudogene and is regulated by HPV E6/E7 and EIF4A3." (PMID 35016697, 2022). "We observed that AGO1/2, EIF4A3, ELAVL1, and PTBP1 were the main RBPs acting in most of the cancer-related and gene regulation enriched pathways." (PMID 35805051, 2022). "In our analysis, 6 out of 18 genes (EIF4A3, RAN, PSMA3, CCNA2, POLR2D, CDC27) were scored as SL hits against RB1 in at least two human cancer cell lines screens." (PMID 33591981, 2021). "In the context of cancer, the EJC components EIF4A3 and RBM8A, have been well-characterized." (PMID 37294214, 2023). "Thus, in this study, we firstly proposed that TCAM1P is cancer/testis (CT) pseudogenes and is regulated by HPV E6/E7 and EIF4A3." (PMID 35016697, 2022). "Since EIF4A3 plays a key role in NMD, EIF4A3-targeted strategies may open a new path for treating cancer and other PTC-related genetic diseases." (PMID 34458150, 2021).
cancer (continued). "This is the first study to demonstrate that the circ-SIRT1/EIF4A3/N-cadherin/vimentin axis promotes the proliferation and EMT of CRC cells, providing a novel therapeutic target and strategy for the treatment of this cancer." (PMID 34660182, 2021). "Remarkably, we could recapitulate cancer-specific mRNA re-splicing in normal cells by knock-down of any of the core EJC proteins, EIF4A3, MAGOH, or RBM8A (Y14), implicating the EJC core as the repressor of mRNA re-splicing often observed in cancer cells." (PMID 34204574, 2021). "Overexpression of DHX15, EIF4A3, and RBM17 splicing factors have been demonstrated in cancer." (PMID 34944912, 2021). "The cooperative regulation of EIF4A3 and WIPI3 in cancer cells may indicate a special spliceosome mechanism that can synchronize rapid cell proliferation based on the maintenance of genomic stability." (PMID 32973867, 2020). "Thus, eIF4A3 and FUS may represent major pan-cancer therapeutic targets." (PMID 35729321, 2022).
infection (5 papers, 2019 to 2026). The state of being infected such as from the introduction of a foreign agent such as serum, vaccine, antigenic substance or organism. "Collectively, these data revealed that potyviruses employ a conserved strategy of recruiting the m6A suppressor eIF4A3 to inhibit m6A modification and thereby prevent viral RNA degradation during infection." (PMID 41505092, 2026). "In contrast, almost 100 transcripts related to genes typically involved in viral protein translation during infection (e.g. rps2, 12, 14; wdr12; rpf2; nip7; eif4; eif4ebp3l; eif4a3; eif4ea; eif4b) were down-regulated." (PMID 35710351, 2022). "Remarkably, this eIF4A3-mediated suppression of m6A is conserved across potyviral infections." (PMID 41505092, 2026).
neurodevelopmental disorder (2 papers, 2022 to 2023). A behavioral and cognitive disorder with onset during the developmental period that involves impaired or aberrant development of intellectual, motor, or social functions. "Apart from the oncogenic role of EIF4A3 in hunman cancers, it is also reported to modulate neurodevelopmental disorders and embryonic stem cell identity." (PMID 37777564, 2023). "For instance, loss-of-function mutations in UPF2, UPF3B, SMG8 and SMG9 genes, and CNVs targeting UPF2, UPF3A, SMG6, EIF4A3, RNPS1 and RBM8A genes, have been implicated in a variety of neurodevelopmental disorders, including DD, ID, ADHD and TAR syndrome." (PMID 35327467, 2022).
gastrointestinal disorders (1 paper, 2024). "Although previous studies showed that EIF4A3 promoted the biogenesis of circRNAs, this is the first to demonstrate that EIF4A3 could be recruited by circRNAs to exert biological functions in gastrointestinal disorders." (PMID 38981023, 2024).
EIF4A3 also shares sentences with these, for which no sentence is quoted: acute myeloid leukemia (2 papers); endometrial cancer (2); Esophageal carcinoma (2); lung adenocarcinoma (2); lymphoma (2); muscle atrophy (2); renal carcinoma (2); brain tumor (1); colon adenocarcinoma (1); esophageal squamous cell carcinoma (1); Facioscapulohumeral dystrophy (1); fibrosis (1); genetic diseases (1); Intellectual disability (1); Papillary Thyroid Cancer (1); pulmonary fibrosis (1); Richieri Costa-Pereira syndrome (1); vaginal carcinoma (1); Wolcott-Rallison syndrome (1).